PIN1 (peptidylprolyl cis/trans isomerase, NIMA-interacting 1)
Diseases named in the same sentence as PIN1 in open-access papers (continued):
Sharing a sentence is not in itself a finding about the gene and the disease.
cancer (continued). "Pin1 is not only overexpressed in cancer cells but also markedly elevated in CAFs, where its expression correlates with desmoplastic features and poor clinical outcomes." (PMID 41322199, 2025). "Pin1 serves as the primary regulator within the intricate network of signaling pathways that contribute to cancer drug resistance." (PMID 41246306, 2025). "Pin1 regulates the function of oncogenes and tumor suppressors, both in cancer cells and surrounding stromal cells." (PMID 41322199, 2025). "Overexpression of Pin1 in patients with cancer directly correlates with lymph node metastasis in those with non-small cell lung cancer, rapid disease progression in those with oral squamous carcinoma, and overall poor clinical outcomes." (PMID 41322199, 2025). "Taken together, these studies identify 164B8 as a potent, targeted Pin1 agent with improved pharmacokinetic properties compared with the parent molecules, while maintaining its Pin1-degrading effect in both cancer cells and CAFs." (PMID 41322199, 2025). "Aside from targeting Pin1, accumulating evidence suggests that suppressing the protein hypersumoylation in cancer stem cells would benefit cancer treatment." (PMID 38167292, 2024). "Pin1 has been found to confer significant resistance to DNA damage-induced apoptosis in cancer cells, potentially inhibiting a range of pro-apoptotic signals." (PMID 39624096, 2024). "The important role that Pin1 plays in both neurodegenerative diseases and cancer is clearer and has been more extensively reviewed." (PMID 39469929, 2024). "Pin1 contributes to cancer development by upregulation of more than 50 oncogenes or proliferation-promoting proteins while downregulating more than 20 tumor suppressors and proliferation-inhibitory proteins." (PMID 38534454, 2024). "Given the upregulation of oncogenic kinases and downregulation of tumor suppressive kinases in cancer, Pin1 overactivation through differential phosphorylation can contribute to oncogenesis." (PMID 38745861, 2024). "This review outlined some key Pin1 small-molecule inhibitors and some of their validation through different cancer models, but they all have their limitations." (PMID 38745861, 2024). "In cancer stem cells, Pin1 stabilizes key transcription factors, thus promoting cell stemness, which drives the retention of a cancer stem-cell phenotype." (PMID 38745861, 2024). "As a central oncogene, Pin1 emerges as a driver of cancer stem cells in breast, prostate, and brain cancers." (PMID 38167292, 2024). "In this review, we will highlight recent advancements in the understanding of Pin1-regulated ubiquitination and its role in cancer and neurodegenerative diseases." (PMID 38727267, 2024). "The oncogenic isomerase Pin1 is highly expressed in many cancers and plays key roles in multiple malignant aspects." (PMID 38167292, 2024). "E2F and neurogenic locus notch homolog protein 1 (Notch1) transcription factors induce Pin1 expression and are known to play an important role in cancer progression by regulating S-phase entry and differentiation, respectively." (PMID 38745861, 2024). "The link between Pin1 and cancer was first suggested by studies showing the overexpression of Pin1 in cancer tissues." (PMID 39202474, 2024). "Specifically, Pin1 promotes cancer progression by increasing the stabilities of numerous oncoproteins and decreasing the stabilities of many tumor suppressors." (PMID 38727267, 2024).
cancer (continued). "In contrast, in cancer, Pin1 is upregulated to promote tumour progression via activation of the Akt signalling pathway [reviewed in Zhou & Lu 2016), but its relationship to tau as a potential mediator or intermediary factor in this has not been assessed." (PMID 39469929, 2024). "Pin1 is widely expressed in a range of cancers and is assumed to play a key role in tumorigenesis by modulating protein function and conformation." (PMID 39624096, 2024). "In summary, Sulfopin is a promising inhibitor that works both in vitro and in vivo to inhibit Pin1, and its activity was validated in different physiologically relevant disease models where it conferred significant anti-cancer effects." (PMID 38745861, 2024). "Excess Pin1 activity can divert substrates from degradation, enabling the enhanced stabilities of oncoproteins and the promotion of tumorigenesis by acting on cancer stem cells as well as stromal cells." (PMID 38727267, 2024). "In this review, we highlight recent advancements in Pin1-regulated ubiquitination in the context of cancer and neurodegenerative disease." (PMID 38727267, 2024). "These attributes position Pin1 inhibitors as valuable assets in the battle against cancer and strong candidates for targeted therapy." (PMID 38318109, 2024). "Pin1 is a unique protein that establishes a direct link between the pathophysiology of AD and several cancer types." (PMID 38534454, 2024). "PIN1 facilitates the functions of multiple oncogenes and abrogates tumor suppressors, and hence its deregulation results in disease, especially cancer." (PMID 38627659, 2024). "Pin1 is frequently upregulated in several human cancers, and its overexpression is correlated with poor prognosis." (PMID 38167292, 2024). "Peptidyl-prolyl cis/trans isomerase NIMA-interacting 1 (Pin1) is overexpressed and/or overactivated in many human cancers and has been shown to play a critical role during oncogenesis." (PMID 38550694, 2024). "Through isomerizing hundreds of substrate proteins, Pin1 functions as a pivotal regulator in multiple aspects in cancers." (PMID 38167292, 2024). "In cancer, Pin1 is often overexpressed and promotes oncogenic signaling pathways, while in AD, its loss contributes to neurodegeneration." (PMID 38534454, 2024). "Sulfopin-dependent inhibition of PIN1 was shown to downregulate the expression of MYC target genes in several cancer cell lines." (PMID 39093942, 2024). "By unravelling the mechanisms regulating deubiquitination and stabilization of Pin1 in GSCs, we provide more molecular targets to impair Pin1 protein stability for cancer treatment." (PMID 38167292, 2024). "Not only can ATRA and ATO act independently to inhibit and degrade Pin1, but in combination they work synergistically for enhanced anti-cancer effects." (PMID 38745861, 2024). "Pin1 is a master regulator of the structure and functions of many phosphorylated proteins; it is overexpressed in most cancers and regulates numerous cancer-driving pathways by specifically isomerizing a key phospho-motif." (PMID 38745861, 2024). "One way in which Pin1-regulated ubiquitination contributes to the metabolic reprogramming of cancer cells is by stabilizing critical transcription factors, such as hypoxia inducible factor (HIF), as reviewed recently by Nakatsu and colleagues." (PMID 38727267, 2024). "Recent advancements in creating Pin1 inhibitors through structure-based drug design and natural compounds, aiming to inhibit cancer activities." (PMID 38534454, 2024). "In this review, we provide a comprehensive summary of the processes involving Pin1 and its mechanisms in the context of cancer therapy." (PMID 39624096, 2024). "Given the importance of such mechanisms in the context of cancer research, in this mini-review, we present a comprehensive summary of the mechanisms of action involving Pin1." (PMID 39624096, 2024).
cancer (continued). "Pin1’s oncogenic functions make it a promising target for cancer therapy, with inhibitors such as ATRA and KPT-6566 showing efficacy in vitro and in vivo." (PMID 38534454, 2024). "Pin1 is overexpressed/overactivated in cancers with the result that numerous oncoproteins are activated and tumor suppressor functions are deactivated." (PMID 38687676, 2024). "As Pin1 is the only phosphorylation-dependent prolyl isomerase, it is solely responsible for regulating the substrates of a vast array of cancer-promoting kinases." (PMID 38745861, 2024). "These discoveries provide multiple drug targets and therapeutic strategies for the treatment of GBMs and potentially other Pin1-driven cancers." (PMID 38167292, 2024). "Juglone is a naturally occurring agent that mediates PIN1 inhibition, offering a novel approach to cancer treatment." (PMID 39202474, 2024). "In this context, recent studies point to the potential effects of phytotherapeutics that inhibit PIN1 in cancer treatment." (PMID 39202474, 2024). "It is because Pin1 stimulates oncogenic pathways that Pin1 inhibitors show great promise in the development of new cancer therapies." (PMID 38687676, 2024). "Our findings provide multiple molecular targets to induce Pin1 degradation and suppress hypersumoylation for cancer treatment." (PMID 38167292, 2024). "In cancer cells, Pin1 gene is overexpressed and contributes substantially to the Warburg effect by enhancing glycolysis and suppressing oxidative phosphorylation." (PMID 38786739, 2024). "The Pin1 gene plays a role in cancer and AD by influencing cell cycle control, signal transduction, DNA damage response, as well as the management of tau and β-amyloid (Aβ) precursor proteins." (PMID 38544686, 2024). "The therapeutic potential of Pin1 inhibition in cancer is discussed, along with the promise and the difficulties in identifying potent, drug-like, small-molecule Pin1 inhibitors." (PMID 38745861, 2024). "This research focused on targeting the distinctive enzyme PIN1, crucial for catalyzing proline isomerization within phospho-serine/threonine-proline motifs, with significant therapeutic implications for cancer treatment." (PMID 38318109, 2024). "We also describe the different inhibitors of Pin1, including natural products and small molecules, and their potential applications in cancer therapy." (PMID 39624096, 2024). "Pin1 can also be dysregulated in cancer through post-translational modifications like phosphorylation and SUMOylation." (PMID 38745861, 2024). "As a valuable therapeutic target in carcinogenesis and drug resistance, Pin1 can serve as an excellent candidate for the development new cancer treatment strategies." (PMID 39624096, 2024). "Pin1 plays a critical role in the development of cancer by inhibiting tumor suppressors and promoting the activation of oncogenes." (PMID 39081443, 2024). "Previous studies on Pin1 have concentrated on its twofold function concerning the advancement of cancer (Pin1 activation) and AD (Pin1 inactivation)." (PMID 38534454, 2024). "Pin1 is a phosphorylation-specific prolyl isomerase that regulates numerous signaling molecules that promote tumor growth in cancer." (PMID 39057063, 2024). "Due to Pin1’s direct involvement with both cancer and AD, it has garnered considerable interest as a potential therapeutic target and warrants further exploration." (PMID 38544686, 2024). "Cancer-driving signaling pathways are typically modulated by protein phosphorylation and dephosphorylation, and this distinctive property of Pin1 enables it to recognize and isomerize phosphorylated Ser/Thr-Pro moiety sequencing signals." (PMID 39624096, 2024).
cancer (continued). "Small-molecule inhibitors have been used to probe the effect of Pin1 inhibition on resistance, and in many cancer types, it has either reversed resistance or sensitized the cancer for treatment with other therapeutic agents." (PMID 38745861, 2024). "Cancer successfully uses Pin1’s role to drive multiple oncogenic pathways through stabilizing oncogenes while turning off tumor suppressors." (PMID 38745861, 2024). "Elevated Pin1 levels often correlate with unfavorable clinical outcomes, underscoring its potential prognostic value in cancer." (PMID 38318109, 2024). "The mechanisms through which cancers acquire resistance are multifaceted, but Pin1 is uniquely situated as a master regulator at the center of a complex network of signaling pathways that drive cancer drug resistance." (PMID 38745861, 2024). "Pin1 enhances signaling pathways in a number of different human cancers and plays a pivotal role in the suppressive mechanisms relevant to cancer treatment." (PMID 39624096, 2024). "The enzyme Pin1 illustrates potential mechanisms, being upregulated in numerous human cancers while downregulated in AD." (PMID 38534454, 2024). "PIN1 is often dysregulated in various cancer types, and overexpression and/or overactivation is associated with a poor clinical prognosis." (PMID 37370134, 2023). "Over the past two decades, several PIN1 inhibitors have been developed, exhibiting pre-clinical in vitro and in vivo activities against human cancers, including HCC." (PMID 36707636, 2023). "ATRA-NPs exerted their potent anti-metastatic effect by inhibiting Pin1 and then simultaneously blocking multiple signaling pathways and cancer epithelial–mesenchymal progression." (PMID 36915713, 2023). "Pin1 correlates closely with the exacerbation of cancers and is, in fact, overexpressed in a wide variety of malignancies, such as prostate, ovarian and pancreatic cancers." (PMID 36583514, 2023). "KPT6566 selectively inhibits Pin1, which influences the turnover and activity of oncogenic and tumor-suppressor proteins in human cancer cells." (PMID 38020885, 2023). "PIN1 is overexpressed in cancer and regulates numerous cancer-driving pathways by controlling the stability of oncogenes and tumor suppressors." (PMID 36899853, 2023). "Pin1 is frequently overexpressed in many human cancers, including HCC, thereby contributing to centrosome amplification, chromosome instability, and tumorigenesis both in vitro and in vivo; indeed, its expression correlates with poor clinical outcomes." (PMID 37404723, 2023). "A recent study demonstrated that Pin1 is overexpressed in most cancers and contributes to tumor progression by mediating multiple signaling factors." (PMID 38089883, 2023). "Many studies have suggested that dementia and site-specific cancers have one or more common molecular mechanisms, such as the PIN1 enzyme and signaling pathway." (PMID 36765585, 2023). "In the study of PDAC, the researchers analyzed tumor samples and found a unique proline isomerase, Pin1, overexpressed in both CAFs and cancer cells." (PMID 36759842, 2023). "The aberrant overexpression of Pin1 in various human tumors promotes tumorigenesis by activating a range of cancer pathways." (PMID 36915713, 2023). "According to the existing research, Pin1 upregulates >50 oncogenes or proliferation-promoting factors while inhibits >20 tumor suppressors or proliferation restraining factors.These features make Pin1 inhibitors an important weapon in the fight against cancer." (PMID 37050909, 2023). "Huh7 and HepG2 are cancer cells, and their Pin1 expression levels are, thus, markedly elevated compared to those in normal hepatocytes." (PMID 37240193, 2023). "Overexpression of Pin1 has been correlated with the poor clinical outcome of cancer patients by affecting multiple oncogenic signaling pathways." (PMID 37508437, 2023).
cancer (continued). "Since increasing evidence has shown that Pin1 is a potential target for cancer therapy, several groups have developed potent antagonists, including chemical compounds, natural products, and peptide drugs, to block Pin1." (PMID 37050909, 2023). "Shortly speaking, in the process of cancer development, PIN1 can regulate the biological function of cells by affecting complex signaling pathways." (PMID 37105032, 2023). "Although Pin1 is overexpressed in multiple human cancers and cancer cell lines, its role in TGCTs remains poorly understood." (PMID 38020885, 2023). "A large-scale human tissue microarray study compared normal and cancerous tissues to reveal that the protein expression level of Pin1 is significantly overexpressed in most common cancers including prostate, breast, lung, and colon cancer." (PMID 37508437, 2023). "Pin1 is highly overexpressed, often > fivefold in many malignant tumors, and facilitates cell cycle progression, making it a potential therapeutic target." (PMID 37849016, 2023). "Since PIN1 is highly expressed in most cancers, particularly cancer stem cells, we investigated the effect of NONO silencing on PIN1 expression." (PMID 37370134, 2023). "Juglone and its derivatives are inhibitors of Pin1 and are effective in reducing chemotherapy resistance due to cancer treatment." (PMID 36770689, 2023). "As such, we detected Pin1 expression in 11 cancer cell lines (A549, HT-29, CHO, HepG2, MG63, HeLa, BEL-7402, MCF-7, and PC3) and a non-cancer cell line MRC5." (PMID 37050909, 2023). "Intriguingly, CI is clinically used in both diseases, we verified that PIN1 is one of the key molecules, which almost acts as the center to regulate the multiple cancer-driving processes." (PMID 37006999, 2023). "As cancers share a common feature of uncontrolled cell proliferation, inhibition of Pin1 has the potential to simultaneously tackle multiple oncogenic signal pathways at several levels." (PMID 37050909, 2023). "The current knowledge is based mostly on data showing that Pin1 is overexpressed/activated in most malignancies and cancer stem cells, with correspondingly poor prognoses." (PMID 37511442, 2023). "Further preclinical studies including PDX in vivo animal models and clinical studies are warranted to explore the therapeutic benefits of targeting the PIN1/CDK1-pVHL axis in the treatment of multiple human cancers with wild-type VHL." (PMID 36813923, 2023). "Firstly, qRT-PCR and Western blot were adopted to detect the expression levels of miR-150-5p and PIN1 in cancer tissue and paracancerous tissues of patients with LSCC, and those in human bronchial epithelial cells (16 HBE) and HEp-2." (PMID 37105032, 2023). "In cancer, PIN1 overexpression and APC/CCDH1 inactivation reinforce each other to promote uncontrolled proliferation and tumorigenesis." (PMID 36711754, 2023). "These included PIN1, which is a propyl isomerase that isomerises specific phosphorylated Ser/Thr-Pro proteins and is overexpressed in various cancer types." (PMID 36707636, 2023). "In this study, we reveal the cyclin-dependent kinase 1 (CDK1) and peptidyl-prolyl cis-trans isomerase NIMA-interacting 1 (PIN1) as two previously uncharacterized regulators of pVHL stability in multiple cancer types harboring wild-type VHL including TNBC." (PMID 36813923, 2023). "Through inhibition of PIN1, it is possible to block multiple cancer-driving pathways with limited side effects." (PMID 37006999, 2023). "Functionally, in addition to Pin1 activating various cancer pathways such as Raf/MEK/ERK, PI3K/Akt, Wnt/β-catenin, NF-κB." (PMID 36770689, 2023). "Peptidyl-prolyl cis/trans isomerase or NIMA-interacting-1 (Pin1) plays a crucial role in development of many human cancers." (PMID 38020885, 2023). "Pin1 is often overexpressed and activated in human cancers and regulates multiple oncogenic signaling pathways, so is a promising potential therapeutic target for TGCTs." (PMID 38020885, 2023).